VNN2 (vanin 2)
Description:
Amidohydrolase that hydrolyzes specifically one of the carboamide linkages in D-pantetheine thus recycling pantothenic acid (vitamin B5) and releasing cysteamine. Involved in the thymus homing of bone marrow cells. May regulate beta-2 integrin-mediated cell adhesion, migration and motility of neutrophil.
Synonyms: FOAP-4; GPI-80
Tractability: Antibody: UniProt places it where antibodies can reach, with high confidence; its Gene Ontology location is reachable by antibodies, with high confidence; UniProt predicts a signal peptide or a membrane-spanning region.
Gene: Protein-coding gene on chromosome 6 (132,743,870 to 132,763,459, reverse strand). Ensembl gene ENSG00000112303.
Subcellular location: Cell membrane
Pathways (Reactome):
Metabolism: Vitamin B5 (pantothenate) metabolism
Metabolism of proteins: Post-translational modification: synthesis of GPI-anchored proteins
Gene Ontology:
Molecular function: pantetheine hydrolase activity; protein binding; hydrolase activity, acting on carbon-nitrogen (but not peptide) bonds, in linear amides
Biological process: pantothenate metabolic process
Cellular component: extracellular region; plasma membrane
Genetic constraint (gnomAD): Loss-of-function variants: 40 observed, 43.22 expected, observed/expected ratio (o/e) 0.93, 90% interval 0.72 to 1.21. The upper end of that interval is the gene's LOEUF score, 1.21, which puts it in group 5 of 6, group 1 being the genes least tolerant of losing a copy. Missense variants: 598 observed, 586.8 expected, observed/expected ratio (o/e) 1.02, 90% interval 0.95 to 1.09. Synonymous variants: 201 observed, 210.62 expected, observed/expected ratio (o/e) 0.95, 90% interval 0.85 to 1.07.
Homologues: Orthologues: chimpanzee VNN2 (99% identical), macaque VNN2 (93% identical), tropical clawed frog vnn2 (57% identical), Drosophila melanogaster Btnd (25% identical), Drosophila melanogaster CG32751 (24% identical), Drosophila melanogaster vanin-like (24% identical), Drosophila melanogaster CG32750 (24% identical). Paralogues in human: VNN1 (62% identical), BTD (38% identical).
Diseases named in the same sentence as VNN2 in open-access papers:
VNN2 is named in the same sentence as 31 diseases in open-access papers, as found by Europe PMC text mining. Sharing a sentence is not in itself a finding about the gene and the disease. The quoted sentences say what the papers report.
periodontitis (4 papers, 2022 to 2025). An acute or chronic inflammatory process that affects the tissues that surround and support the teeth. "The correlation analysis between VNN2 and indicators of β2 integrin-dependent neutrophil adherence and migration further provided evidence to the contribution of VNN2 through regulating neutrophil migration by associating with Mac-1 (CD11b/CD18) on the human neutrophil surface in periodontitis." (PMID 36527111, 2022). "The findings revealed that the expression levels of VNN1 and VNN2 were significantly upregulated in the periodontitis cohort." (PMID 38491529, 2024). "The results supported that VNN1 and VNN2 were enriched in gingival tissues affected by periodontitis, especially in the part of connective tissues." (PMID 36527111, 2022). "Our study demonstrated upregulation of Vanins in periodontitis and the potential contribution of VNN2 to periodontitis through neutrophils-related pathological processes." (PMID 36527111, 2022). "Assessment using western blot and immunohistochemistry presented significant upregulations of VNN1 and VNN2 in periodontitis (p < 0.05)." (PMID 36527111, 2022). "Taken together, VNN2 was suggested to potentially influence the inflammatory response via regulating β2 integrin-dependent neutrophil adherence and migration in periodontitis." (PMID 36527111, 2022). "Meanwhile, four genes, including FPR1, AQP9, BCL2A1, and VNN2 showed significantly higher expression in periodontitis patients and were strongly correlated with neutrophil infiltration, emerging as central to diagnosis and understanding of periodontitis." (PMID 41009952, 2025). "Furthermore, VNN2 was positively correlated with indicators of neutrophils, indicating the potential contribution of VNN2 to periodontitis via affecting neutrophil adherence and migration during immune response." (PMID 36527111, 2022). "What’s more, the VNN2 might interact with neutrophil during periodontitis pathogenesis, with positive evidence between VNN2 and neutrophil-related biomarkers, MPO and indicators of β2 integrin-dependent neutrophil adherence and migration." (PMID 36527111, 2022). "Results suggested that the Vanins were upregulated in the gingival tissues from patients with periodontitis when compared with periodontal healthy individuals, among which two members, VNN1 and VNN2 were elevated on both the genetic and protein levels." (PMID 36527111, 2022). "Generally speaking, expression levels of VNN1, VNN2 and VNN3 were higher in gingival tissues from periodontitis patients at the genetic level in both RT-qPCR and GEO dataset analysis." (PMID 36527111, 2022).
COVID-19 (3 papers, 2021 to 2023). A disease caused by infection with severe acute respiratory syndrome coronavirus 2. "This was expected since mRMR tries to decrease the number of redundant features from the same cluster but also confirms the significance of VNN2 in the diagnosis of COVID-19." (PMID 38027840, 2023). "while the most significant contributing protein for COVID-19 diagnosis was VNN2 (vanin 2)." (PMID 38027840, 2023). "Interestingly, the results were consistent with those in COVID-19; 27 of the IRGs were highly expressed in myeloid cells, except Icam1, Lyn, Cybb, Casp1, Gbp1, Vnn2, Socs3, Bcl2a1 and Lcn2 genes." (PMID 36817436, 2023).
prostate carcinoma (3 papers, 2021 to 2023). A carcinoma that arises from epithelial cells of the prostate gland. "A urologic cancer-based study provided some mechanistic insight into VNN2’s impact, in which VNN2 was found to promote non-adhesive proliferation and IL-1beta production in prostate cancer cell lines and generally was correlated with poor survival outcomes." (PMID 36428698, 2022).
glioma (2 papers, 2022 to 2023). A benign or malignant brain and spinal cord tumor that arises from glial cells (astrocytes, oligodendrocytes, ependymal cells). "While MDSCs are known to inhibit CD8+ T cell proliferation, this study described an inverse association between CD14+ monocytes expressing VNN2 and glioma patient’s tumor grade potentially highlighting a role for VNN2 in less aggressive tumors." (PMID 36428698, 2022). "An important recent observation regarding MDSCs in gliomas is the demonstration of high expression of vascular non-inflammatory molecule 2 (vanin-2, VNN2) by monocyte-derived M-MDSCs in the peripheral blood of healthy individuals." (PMID 38275375, 2023). "In patients with gliomas, the expression of VNN2 in M-MDSCs in peripheral blood was significantly reduced compared with healthy controls, and the degree of reduction in VNN2 expression was inversely correlated with glioma grade." (PMID 38275375, 2023). "The potential role of vanin-2 as a useful marker for tumor diagnosis and even its role as a therapeutic circuit to curb the immunosuppressive capacities of M-MDSCs in gliomas has been addressed." (PMID 38275375, 2023). "An important observation is the downregulation of the surface ectoenzyme vanin-2 (VNN2) on M-MDSCs in the peripheral blood of patients with high-grade gliomas." (PMID 38275375, 2023). "The reason for the reduced VNN2 expression in the biological response of M-MDSCs to gliomas has not yet been investigated, but the detection of CD14+/VNN2high MDSCs in peripheral blood is considered an additional useful marker in the diagnostic spectrum of tumor diagnosis." (PMID 38275375, 2023). "Vanin-2 is expressed on normal M-MDSCs and is involved in transendothelial migration of neutrophils, whereas the reasons for its downregulation in M-MDSCs from glioma patients are not clear to date." (PMID 38275375, 2023).
osteosarcoma (2 papers, 2023 to 2024). A usually aggressive malignant bone-forming mesenchymal neoplasm, predominantly affecting adolescents and young adults. "The upregulation of VNN2 can inhibit the proliferation, migration, and invasion of human osteosarcoma cells and induce their apoptosis." (PMID 39041652, 2024). "The results of this study showed that miR-106a is upregulated in human osteosarcoma cells and the knockdown of miR-106a mediated tumor progression at least partially by targeting VNN2 in osteosarcoma." (PMID 37627777, 2023).
acute myocardial infarction (1 paper, 2022). Necrosis of the myocardium, as a result of interruption of the blood supply to the area. "Literature retrieval results uncovered that the interaction between hubgenes (VNN2, S100A12) and acute myocardial infarction has not been well established previously." (PMID 35722095, 2022).
dementia (1 paper, 2021). Loss of intellectual abilities interfering with an individual's social and occupational functions. "Since chronic inflammation is considered to be one of the main pathological mechanisms of diabetes and dementia, higher expression of VNN2 may be related to pathological events." (PMID 33597859, 2021).
diabetes (1 paper, 2021). "Numerous functional studies demonstrate a role for Vanin genes [Vanin-1 (VNN1), Vanin-2 (VNN2), Vanin-3 (VNN3)] in inflammation, oxidative stress, cell migration, and various diseases such as diabetes and CVDs." (PMID 33597859, 2021).
esophageal cancer (1 paper, 2023). A primary or metastatic malignant neoplasm involving the esophagus. "VNN2 was discovered to be up-regulated in a human metastasizing esophageal cancer cell line (T.Tn-AT1) in comparison to the parental non-metastasizing cell line (T.Tn), emphasizing its significance in metastasis." (PMID 37502362, 2023).
hyperlipidemia (1 paper, 2021). "Studies have shown that the gene expression level of VNN2 changed in monocytes from hyperlipidemia patients under atorvastatin treatment, which is a prescription medication used to improve cholesterol metabolism." (PMID 34567069, 2021).
Insulin resistance (1 paper, 2023). Increased resistance towards insulin, that is, diminished effectiveness of insulin in reducing blood glucose levels. "In this report, the researchers explored the relationship between changes in Vanin-2 protein expression and obesity or insulin resistance (IR) in patients." (PMID 38156278, 2023). "This study aims to explore the expression patterns and potential mechanisms of Vanin-2 in individuals with obesity and insulin resistance." (PMID 38156278, 2023). "Furthermore, this study’s data show that serum Vanin-2 concentration is elevated in patients with insulin resistance." (PMID 38156278, 2023). "Therefore, we hypothesize that Vanin-2 may promote IL-18 secretion to maintain weight homeostasis and prevent excessive weight gain in individuals with obesity and insulin resistance." (PMID 38156278, 2023).
lung carcinoma (1 paper, 2020). "Our study revealed that the CD20+ B cells in the microenvironment of lung cancers produce a high level of VNN2 and SERPINA9 and directly inhibit the growth of NSCLC cells." (PMID 32580738, 2020).
male infertility (1 paper, 2023). The inability of the male to effect fertilization of an ovum after a specified period of unprotected intercourse. "A total of five proteins (PFS males) have been used as potential markers of male infertility, namely B2M, complement-3 (C3), CFB, VNN2, and CTSS." (PMID 37969811, 2023).
melanoma (1 paper, 2022). A malignant, usually aggressive tumor composed of atypical, neoplastic melanocytes. "Considering the limited work pertaining to VNN2′s significance in melanoma, mechanistic studies describing its effect on the tumor immune microenvironment are needed to establish practical recommendations." (PMID 36428698, 2022). "Additionally, through transcriptomic data, we were able to identify novel genes (GSTA3 and VNN2) that could lead to better stratification of potential responders to ICIs in melanoma." (PMID 36428698, 2022).
Obesity (1 paper, 2023). Accumulation of substantial excess body fat. "Moreover, Vanin-2 may play a role in regulating obesity-related inflammation and contribute to the development of protective metabolic disorders associated with obesity." (PMID 38156278, 2023). "Serum Vanin-2 is a highly effective biomarker for assessing adipose tissue inflammation in obesity and has the potential to serve as a predictor of bariatric surgery outcomes." (PMID 38156278, 2023). "In future studies, we plan to further explore the correlation and mechanism between the Vanin family and obesity by studying the relationship between Vanin-1 and Vanin-2 factors and obesity, and potentially constructing human gene knockout mice." (PMID 38156278, 2023). "Serum levels of Vanin-2 were found to be significantly increased in individuals with overweight/obesity (OW/OB) group (controls 438.98 ± 72.44, OW/OB 530.89 ± 79.39 ug/L; p < 0.001)." (PMID 38156278, 2023). "In conclusion, while the exact function of Vanin-2 is yet to be determined, the data suggest that dysfunctional adipose tissue in obesity leads to increased expression and secretion of Vanin-2." (PMID 38156278, 2023). "We hypothesized that serum Vanin-2 concentrations would increase with the severity of obesity." (PMID 38156278, 2023).
rheumatoid arthritis (1 paper, 2022). A chronic, systemic autoimmune disorder characterized by inflammation in the synovial membranes and articular surfaces. "For patients with rheumatoid arthritis, VNN2 presents high concentrations in synovial fluids, indicating its role in inflammatory disease." (PMID 36527111, 2022).
tumor (8 papers, 2021 to 2023). "The VNN2 protein is essential for cell transendothelial migration and is linked to non-adhesive proliferation, which raises the possibility that it contributes to tumor anoikis resistance." (PMID 37502362, 2023). "Several studies have indicated that the seven key prognostic genes identified in this study for UCEC, including TSPYL5, VNN2, ANXA1, and DCAF12L1, are associated with tumor occurrence and development." (PMID 37363398, 2023). "Tumor mutation burden, GSTA3, and VNN2 were the highest contributing features." (PMID 36428698, 2022). "Another aspect of VNN2’s role in the tumor immune microenvironment is its functionality with MDSCs." (PMID 36428698, 2022).
cancer (3 papers, 2021 to 2023). A tumor composed of atypical neoplastic, often pleomorphic cells that invade other tissues. "Therefore, the cancer suppression mechanism that includes VNN2 is not only limited to mammals, and the same mechanism may exist in the serpent." (PMID 34745239, 2021). "Recent studies have discovered a relationship between glycosylphosphatidylinositol (GPI)-anchored protein 80 (GPI-80)/VNN2 (80 kDa GPI-anchored protein) and malignant tumors." (PMID 34769456, 2021).
infection (1 paper, 2025). The state of being infected such as from the introduction of a foreign agent such as serum, vaccine, antigenic substance or organism. "The PPI observed that the hub genes with the largest number of associated nodes in the weighted network played a crucial role in the immune cell recruitment and activation after infection, such CXCR1, VNN2, BST1, CREM, IL1R1, and CD48." (PMID 39692191, 2025).
VNN2 also shares sentences with these, for which no sentence is quoted: acute lymphoblastic leukemia (1 paper); bladder cancer (1); chondrosarcoma (1); hematological malignancies (1); hepatocellular carcinoma (1); injury (1); ischemic stroke (1); kidney cancer (1); lung adenocarcinoma (1); metabolic disorders (1); polycystic ovary syndrome (1); vascular dementia (1).